ANGPT2 (angiopoietin 2)
Diseases named in the same sentence as ANGPT2 in open-access papers (continued):
Sharing a sentence is not in itself a finding about the gene and the disease.
COVID-19 (49 papers, 2020 to 2026). A disease caused by infection with severe acute respiratory syndrome coronavirus 2. "ANGPT2 has been previously linked with vascular dysfunction and poor outcomes in COVID-19 and H1N1 infections." (PMID 41200555, 2025). "The clinical association between ANGPT2 levels and disease severity in COVID-19 has been extensively demonstrated." (PMID 38803346, 2024). "Our data suggest that ANGPT2 levels are not only a biomarker for disease severity, but also causal and contribute to hypercoagulation in critically ill COVID-19 patients." (PMID 35740360, 2022). "In fact, previous reports showed that during the acute phase of COVID-19, sE-selectin, Angiopoietin-2 and sICAM-1 are associated with disease severity." (PMID 35189887, 2022). "COVID-19 was associated with seemingly unperturbed barrier integrity (angiopoietin-2/1 ratio), enhanced glycocalyx degradation (syndecan-1) and elevated levels of angiogenic factors (PDGFs)." (PMID 35660785, 2022). "Our data suggest a novel in vivo mechanism for Angiopoietin-2 in COVID-19-associated hypercoagulation, implicating that Angiopoietin-2 inhibitors may be effective in the treatment of hypercoagulation in severe COVID-19 infection." (PMID 35740360, 2022). "However, upregulation of genes responsible for ‘intussusceptive angiogenesis’ was more predominant in the specimens of COVID-19 subjects with angiopoietin-2 being strongly implicated in these patients." (PMID 33082849, 2020). "Moreover, the results indicate enhanced activation of the alternative complement pathway is most prevalent in patients with severe COVID-19 and is associated with markers of endothelial injury (i.e., angiopoietin-2) as well as hypercoagulability (i.e., thrombomodulin and von Willebrand factor)." (PMID 34446527, 2021). "In parallel, elevated plasma angiopoietin-2 (Ang2), an inflammatory cytokine, is a strong predictor of death in infection-mediated acute respiratory distress syndrome and correlates with COVID-19 disease severity." (PMID 40106444, 2025). "In our study, we analyzed the Angiopoietin-1 and Angiopoietin-2 indexes and Angiopoiten-2/Angiopoiten-1 ratio as indicators that will serve as a screening tool for severity in COVID-19 patients in delta and omicron waves." (PMID 38785513, 2024). "The same group demonstrated that plasma from patients with COVID-19 was capable of inducing gene expression of several mediators of immunothrombosis, including ANGPT2 and F3, in cultured endothelial cells." (PMID 38803346, 2024). "Patients with COVID-19-induced ARDS have higher serum levels of endothelial damage markers such as angiopoietin-2, intercellular adhesion molecule-1, vascular cell adhesion molecule-1, P-selectin, and E-selectin than patients with other types of ARDS." (PMID 39408067, 2024). "This is supported by an increased expression of Angiopoietin 2 in COVID-19 hearts on a gene expression level as well as on protein level, detected by IHC, compared to controls." (PMID 36371548, 2023). "ANGPT-2 is being studied as a marker of endothelial injury and severity of COVID-19, and its elevated plasma levels predict worse outcomes." (PMID 36992415, 2023). "The ANGPT-2 showed an increased tissue expression (p = 0.0055) in the COVID-19 compared to the CONTROL group." (PMID 36992415, 2023). "The high tissue expression of ANGPT-2 in the COVID-19 and H1N1 groups compared to the CONTROL group suggest its involvement in inflammation and vascular damage caused by respiratory infections." (PMID 36992415, 2023). "The findings of this study and previous ones reinforce the need for further studies to better understand the role of ANGPT-2 and other markers in diagnosing and treating respiratory infections such as COVID-19 and H1N1pdm09." (PMID 36992415, 2023). "This study found that there are activated endothelial cells and high levels of biomarkers of blood vessel damage (ICAM-1, ANGPT-2, IL-1β) in severe COVID-19 cases." (PMID 36992415, 2023).
COVID-19 (continued). "Earlier studies showed that ANGPT2 is elevated in COVID-19 patients and correlates to disease severity." (PMID 35740360, 2022). "Microcirculation is also challenged during the COVID-19 disease course, as demonstrated both by elevated plasma levels of angiopoietin 2 and by the in vivo demonstration of a reduction in small-vessel density." (PMID 35956186, 2022). "VWF was significantly (p < 0.0001) elevated in COVID-19 patients compared to healthy controls and correlated (p < 0.05) to ANGPT2." (PMID 35740360, 2022). "Our data show that circulating ANGPT2 levels are increased in critically ill COVID-19 patients, and that ANGPT2 continues to increase over time in the ICU." (PMID 35740360, 2022). "The inflammatory markers CRP, TNFa, IL6, and ferritin were all elevated in COVID-19 patients at admission, and TNFa showed significant correlation with ANGPT2 (p < 0.01)." (PMID 35740360, 2022). "We found that Angiopoietin-2 levels were increased in COVID-19 patients in correlation with disease severity, hypercoagulation, and mortality." (PMID 35740360, 2022). "In conclusion, we show that the ANGPT2 levels in critically ill COVID-19 patients correlate with severity of disease, hypercoagulation, and mortality." (PMID 35740360, 2022). "To investigate the role for ANGPT2 in COVID-19-mediated coagulopathy, we studied plasma from critically ill COVID-19 patients at two time points, together with clinical features." (PMID 35740360, 2022). "Angiopoietin-2 (Ang-2) is a marker of endothelial activation and a good predictive factor for intensive care unit admission of COVID-19 patients." (PMID 36140343, 2022). "In line with this, we found that COVID-19 patients with acute kidney injury (AKI) had higher ANGPT2 levels (p = 0.044), and that the ANGPT2 inversely correlated with eGFR (creatinine) (p < 0.0001)." (PMID 35740360, 2022). "Increased plasma levels of the inflammatory cytokine and TIE2 receptor antagonist Angiopoietin-2 were reported in severely ill COVID-19 patients." (PMID 35740360, 2022). "Angiopoietin-2 levels were also significantly elevated in groups 6/7 and 8 relative to all other hospitalized COVID-19 outcome groups." (PMID 33692097, 2021). "The elevation of angiopoietin-2, thrombomodulin, endothelin-1, and vWF-A2 in fatal COVID-19 cases provides evidence for the involvement of endothelial injury in COVID-19." (PMID 33692097, 2021). "Studies have revealed angiopoietin-2 induced inflammatory intussusceptive angiogenesis along with diffuse alveolar damage in the lung specimens of COVID-19 patients." (PMID 33082849, 2020). "The rationale for this approach is that circulating levels of angiopoietin-2 (ANG2) are abnormally elevated in severe COVID-19 patients." (PMID 32629875, 2020). "Another mechanism by which ANGPT2 could contribute to the prothrombotic state observed in COVID-19 is by thrombomodulin-dependent inhibition of the protein C pathway, as recently postulated." (PMID 38803346, 2024). "Interestingly, in our cohort, patients with ANGPT2 levels higher than 5,000 pg/mL at admission showed both higher counts of TF+ EVs from endothelial cells, as well as higher TF procoagulant activity, reinforcing the concept that ANGPT2 could be associated with TF expression in COVID-19." (PMID 38803346, 2024). "It has previously been shown that ANGPT2 levels above 5,000 pg/mL could identify patient with a worse prognosis among COVID-19 ICU patients." (PMID 38803346, 2024). "Dexamethasone decreases the ratio of angiopoietin-2 to angiopoietin-1, thereby promoting endothelial stabilization and reducing endothelial cell apoptosis, which is critical in reducing mortality in critically ill COVID-19 patients." (PMID 39861839, 2024). "This absence of discrimination of VEGF-A, according to the prognosis of COVID-19 patients, has already been described in small cohort studies, contrary to other endothelial biomarkers, such as angiopoietin-2 or the Intercellular Adhesion Molecule type 1 (ICAM-1)." (PMID 35956186, 2022).
COVID-19 (continued). "In COVID-19, recent data show that ANGPT2 levels correlate with the severity of disease." (PMID 35740360, 2022). "In the present study, we measured ANGPT2 and other parameters in plasma at two different timepoints (admission, and after 10 days) to evaluate changes over time in a selected cohort of 61 critically ill COVID-19 patients." (PMID 35740360, 2022). "Furthermore, we measured plasma concentrations of ANGPT2 and evaluated coagulation parameters in relation to hypercoagulation and clinical outcome in a cohort of critically ill COVID-19 patients." (PMID 35740360, 2022). "Importantly, ANGPT2 administration resulted in circulating ANGPT2 levels equivalent to that of plasma from COVID-19 patients." (PMID 35740360, 2022). "Our results for ANGPT2 in COVID-19 patients are in line with recently published data." (PMID 35740360, 2022). "In the present study, we aimed at investigating the novel mechanism of ANGPT2 inhibition of TM in vivo, and if this could be an additional mechanism for hypercoagulation in critically ill COVID-19 patients." (PMID 35740360, 2022). "Our data suggest that inhibition of ANGPT2 inhibition may be explored as a therapeutic approach in COVID-19 and other diseases with hypercoagulation." (PMID 35740360, 2022). "Moreover, angiopoietin-2 released from damaged endothelial cells is also associated with hypercoagulability and is a relevant predictive factor for ICU admission in COVID-19 patients." (PMID 34829920, 2021). "Besides VEGF-A, another essential vascular regulator, angiopoietin 2, is currently being considered as a therapeutic target in COVID-19." (PMID 32629875, 2020). "Finally, based on an initial series of 40 COVID-19 hospitalized patients and on an independent cohort of 32 COVID-19 patients, we recently reported the interest of angiopoietin-2, a marker of endothelial activation, for predicting the need for ICU admission." (PMID 32676824, 2020). "Angiopoietin-2 may be a predictive factor for intensive care unit admission in COVID-19 patients." (PMID 36289725, 2022). "Studies have shown the benefits of corticosteroids, such as dexamethasone, in reducing mortality in COVID-19 patients and reducing biomarkers such as ICAM-1 and ANGPT-2." (PMID 36992415, 2023). "Conversely, angiogenic compounds such as VEGF or angiopoietin-2 were significantly downregulated in non-PE post-COVID-19 subjects compared to PE." (PMID 38324145, 2024). "In addition, severe COVID-19 patients have increased circulating levels of angiogenic factors, such as VEGF-A, ANGPT1, ANGPT2, and TGF-β." (PMID 36769357, 2023). "In line with our findings, angiopoietin-2/1 ratios were lower in critically ill COVID-19 patients compared with non-COVID-19 patients in the intensive care unit." (PMID 35660785, 2022). "MiRNAs that were downregulated in serum of COVID-19 patients mainly target genes promoting angiogenesis (e.g., VEGFA, ANGPT2, COL4A1, FGF2, ZEB1), apoptosis, autophagy, stress response (e.g., ATG12, ATG14, ATG2B, SOD2, TXNIP), and inflammation (e.g., CXCL9, CXCL10, IL1R1, TNF)." (PMID 36032130, 2022). "As per univariate and multivariate prognostic analyses, a few important genes, including ALPL, ANGPT2, CD4, G6PD, SERPINE1 and TNNI3, may serve as independent prognostic factors for HCC patients with COVID-19." (PMID 36275701, 2022). "In addition, other biomarkers of endotheliopathy, such as angiopoietin 2, would have been worth evaluating in our study since it was found as a predictive biomarker of ICU admission in COVID-19 patients." (PMID 34422854, 2021). "However, biomarkers of endothelial damage, such as thrombomodulin, vWF, angiopoietin 2, and PAI1, are often elevated in COVID-19 patients, and have prognostic relevance." (PMID 34451848, 2021).
COVID-19 (continued). "Additionally, 13 of 55 angiogenic proteins including TIMP-1, uPA, VEGF, MMP-8/9, CXCL4/16, Endoglin, Angiogenin or Angiopoietin-2 were uniquely downregulated in 3-months post-COVID-19 patients without PE compared to those who suffered a PE." (PMID 38324145, 2024).
melanoma (35 papers, 2009 to 2024). A malignant, usually aggressive tumor composed of atypical, neoplastic melanocytes. "High levels of TIE-2+ M-MDSC were linked to reduced effectiveness of melanoma-specific T-cell responses, with ANGPT2 enhancing the suppressive ability of these cells." (PMID 39138146, 2024). "The study also indicated that an increased presence of TIE-2+ M-MDSC and ANGPT2 in blood is associated with poor prognosis in melanoma." (PMID 39138146, 2024). "In human and murine melanomas, ANGPT2 upregulation was associated with cytotoxic T-cell exclusion and immune evasion, a phenotype reversed upon pharmacological inhibition of this factor." (PMID 37887354, 2023). "A higher amount of ANGPT2 was also associated with poor outcomes in melanoma (70% vs 87% alive at 24 months, p = 0.065), in line with the literature." (PMID 35935946, 2022). "The high rate of these cells was associated with low melanoma-specific T-cell responses, and ANGPT2 increases the ability of TIE-2+ M-MDSC to suppress melanoma-specific T-cell functions." (PMID 35935946, 2022). "In melanoma, one study demonstrated high levels of circulating ANGPT2 to be associated with poor patient overall survival." (PMID 31069961, 2019). "Biomarkers of response previously explored include angiopoietin-2 (ANGPT2) in melanoma and polybromo-1 (PBRM1) and polybromo-associated barrier-to-autointegration factor (PBAF) in renal cell carcinoma (RCC)." (PMID 31464611, 2019). "The association between hematogenous metastatic spread of melanomas and high expression of ANGPT2 and TIE1 reported here is consistent with these observations." (PMID 29017512, 2017). "Both IL-10 and ANGPT2 are contained in transcriptional signatures associated with resistance against anti-PD-1 antibodies in melanoma patients, indicating that they rapidly act on the immune regulatory mechanism and can promote immune escape and, ultimately, tumor growth." (PMID 35681453, 2022). "ANGPT2, also known as vascular destabilizing factor angiopoietin-2, was recently observed to destabilize the peripheral vasculature in immune-excluded melanoma, thereby restricting intra-tumoral T-cell accrual." (PMID 39107856, 2024). "Collectively, these results support that TIE-2+ M-MDSC/ANGPT2 axis represents a potential immune escape mechanism in melanoma." (PMID 35935946, 2022). "In a melanoma mouse model of lung metastasis, primary tumors disrupt pulmonary vascular stability by upregulation of angiopoietin-2 (ANG-2), MMP3, and MMP10 in pulmonary blood vessels." (PMID 36237333, 2022). "Thus, a high level of TIE-2+ M-MDSC/ANGPT2 in peripheral blood is associated with impaired antitumor T-cell responses in advanced melanoma, suggesting that this proangiogenic pathway may suppress tumor-specific T cell in melanoma." (PMID 35935946, 2022). "This is also in accordance with the complete impairment of spontaneous anti-melanoma T-cell responses observed in melanoma patients harboring both ANGPT2 and TIE-2+ M-MDSC-rich blood." (PMID 35935946, 2022). "In conclusion, this study in melanoma shows the ability of TIE-2+ M-MDSC to suppress antitumor T-cell function through ANGPT2 stimulation." (PMID 35935946, 2022). "The distribution of the TIE-2+ M-MDSC rate toward the melanoma stage correlated with the serum level of ANGPT2." (PMID 35935946, 2022). "An increase in serum ANGPT2 was also observed in patients with advanced melanoma treated with anti-PD-1 antibodies." (PMID 35681453, 2022). "It has been previously reported that circulating level of Angiopoietin-2 (Ang-2) protein in melanoma patient sera closely correlates with disease progression." (PMID 30634628, 2019). "We examined the level of cEPCs, vascular endothelial growth factor (VEGF), and angiopoietin-2 in the blood of sarcoma and melanoma patients before and after isolated limb perfusion (ILP) with or without recombinant human tumor necrosis factor-α (rhTNF-α)." (PMID 22948772, 2013).